S100A9 (S100 calcium binding protein A9)
Diseases named in the same sentence as S100A9 in open-access papers (continued):
Sharing a sentence is not in itself a finding about the gene and the disease.
systemic sclerosis (9 papers, 2017 to 2025). A chronic disorder, possibly autoimmune, marked by excessive production of collagen which results in hardening and thickening of body tissues. "Interestingly, CCN2 expression, like S100A9, is increased in the epidermal layers of systemic sclerosis skin, a fibrotic disease state associated with TNIP1 SNPs in patient genomes and TNIP1 protein deficiency in lesional skin." (PMID 32377162, 2020). "Infact, among S100 A proteins, S100A7, S100A8, S100A9, S100A12 have been already described as differentially expressed in other systemic autoimmune diseases and particularly in Systemic Sclerosis." (PMID 31249499, 2019). "Interestingly, we discovered that PQD, a selective S100A9/TRL4 binding blocker, has been approved by the FDA for treating systemic scleroderma and has shown safety and efficiency in clinical trials treating other autoimmune/inflammatory diseases." (PMID 39107960, 2024).
acute pancreatitis (8 papers, 2021 to 2026). An acute inflammatory process that leads to necrosis of the pancreatic parenchyma. "As supported by previous studies, genes like S100A12, S100A9 and IL-1B hold substantial value as markers for predicting the severity of Acute Pancreatitis, in line with our research results." (PMID 39372399, 2024). "In acute pancreatitis, upregulation of S100A9 induces cell injury and inflammatory response through activating NLRP3 via targeting VNN1-mediated ROS release." (PMID 36527111, 2022). "S100A8 and S100A9 are overexpressed in acute pancreatitis (AP), CP, and PC tissues, but they are rarely expressed in CP tissues with severe fibrosis, normal pancreatic tissues, and ductal cells." (PMID 34527585, 2021). "Adoptive transfer of acute pancreatitis-derived exosomes into healthy mice reproduced lung injury, whereas exosomes lacking S100A9 or from Kupffer cell-depleted acute pancreatitis mice caused markedly less pathologic alterations." (PMID 42128052, 2026).
amyloid (8 papers, 2010 to 2023). "The main goal of this research is to demonstrate that S100A9, in addition to commonly perceived Aβ peptide, may be a leading causative component of the amyloid-neuroinflammatory cascade, triggered in TBI and presenting the risk for AD and other neurodegeneration disease development." (PMID 30150640, 2018). "S100A9’s role in neurodegenerative disease is the subject of much investigation, as studies of S100A9 gene knockdowns in mice AD models have revealed a significant reduction in amyloid load and improved cognitive function." (PMID 37686007, 2023). "S100A9 is a pro-inflammatory protein that co-aggregates with other proteins in amyloid fibril plaques." (PMID 35743221, 2022). "In Tg2576 mice, there is improved memory function and neuropathology, accompanied by reduced Aβ and amyloid plaque burden after S100A9 was knocked out." (PMID 29942307, 2018). "Similar to the AD hippocampi, the neocortical areas of AD brains have also shown an abundance of Aβ and S100A9 amyloid plaques, in which the immunostaining pattern for Aβ, S100A9 and fibrillar antibodies were perfectly overlapped." (PMID 24240735, 2014). "At two months after injection, we found that knockdown of S100a9 expression had improved the cognition decline of Tg2576 mice in the water maze task, and had reduced amyloid plaque burden." (PMID 20098622, 2010). "S100A9 is highly expressed in glial cells and promotes amyloidosis and amyloid-β (Aβ) aggregation." (PMID 29942307, 2018). "S100A9 could be a common denominator in a broad variety of inflammation-dependent amyloidoses, which may develop in various tissues and organs of the human body from the brain to the aging prostate." (PMID 29866153, 2018). "Interestingly, S100A9 knockdown attenuated memory impairment and reduced amyloid plaque burden in an AD mouse model." (PMID 30150640, 2018). "In an AD mice model S100A9 production was induced by both Aβ peptide and the C-terminal fragment of the amyloid precursor protein, while S100A9 knockdown attenuated memory impairment and reduced amyloid plaque burden." (PMID 24240735, 2014). "S100A9 can form amyloid fibrils in vitro and in vivo, which might be related to amyloidoses." (PMID 35743221, 2022). "Indeed, S100A9 and Aβ immunostaining patterns were overlapped as shown over the large brain tissue area enriched with plaques and encircled by blue line and in the magnified views of particular amyloid plaques." (PMID 30150640, 2018). "Secretion of S100A9 during inflammation has previously been reported to enhance the formation of amyloid plaques, and our data now suggest that deamidation of this protein could be a key event in amyloidosis in the human brain." (PMID 26892330, 2016). "In all individuals both S100A9 and Aβ precursor-plaques were relatively new lesions not reactive with amyloid-specific antibodies and dye h-FTAA, as they were developed on a time scale much shorter than required for AD senile plaque formation." (PMID 30150640, 2018). "Therefore, the amyloid plaques of S100A9 rapidly developed in TBI brain, in fact, can serve as the precursors of AD amyloid plaques, linking TBI and AD via the amyloid cascade mechanism." (PMID 24240735, 2014). "Moreover, in 50% AD cases we have found specific type of amyloid plaques, which were reactive only with S100A9, but not Aβ antibodies." (PMID 30150640, 2018).
fibrosis (8 papers, 2015 to 2025). the formation of excess fibrous connective tissue in an organ or tissue in a reparative or reactive process. "Patient BAL samples showed the same directional trend, with fibrosis patients exhibiting higher expression (p < 0.05 for PN-1, p < 0.0001 for S100A9)." (PMID 41410848, 2025). "The impacts of global deletion of S100A9 on cardiac fibrosis were also corroborated by Masson's staining, immunohistochemical analysis and immunofluorescence staining." (PMID 40860162, 2025). "S100A8 and S100A9 are also up‐regulated in K5‐R1/R24, 8 and to a similar extent in K5‐R1/R2/R3 mice, and these cytokines likely contribute to the dermal fibrosis." (PMID 31830366, 2020). "Across all three settings, key profibrotic markers (FAPα, CD44, S100A9, CTGF and PDGF) were increased under TOX exposure or established fibrosis and were reduced either by RAGE antibody treatment or by clinical improvement." (PMID 41410848, 2025). "The expression of S100A8, S100A9, S100A8/A9, CCL20, and IL-17, detected by ELISA, is significantly increased in NASH patients with fibrosis in comparison with controls." (PMID 26273651, 2015).
Hypertension (8 papers, 2019 to 2026). The presence of chronic increased pressure in the systemic arterial system. "Furthermore, a study has found that upon the initial day of angiotensin II infusion in mice, there is a substantial upregulation of S100A9 expression, which consequently contributes to the development of hypertension‐induced cardiac injury caused by angiotensin II." (PMID 38504474, 2024). "Patients with low 1-year LV midwall function had higher heart rate, more often hypertension and higher levels of both hsCRP, calprotectin S100A9 and total SAA preoperatively (all p < 0.05)." (PMID 38273044, 2024). "These compelling findings underscore the potential of both S100A9 as critical indicators for monitoring the occurrence and progression of hypertension." (PMID 38504474, 2024). "Some of the modulated proteins in saliva such as HSPA8 or S100A9 have been previously related to DM complications such as hypertension or micro-vascular alterations, while others such as S100A2 and S100A11 are described in DM here for the first time." (PMID 33271797, 2020). "In other hypertensive disorders, S100A9 also plays a pivotal role." (PMID 38504474, 2024).
osteosarcoma (8 papers, 2016 to 2025). A usually aggressive malignant bone-forming mesenchymal neoplasm, predominantly affecting adolescents and young adults. "The aim of the study was to evaluate the role of S100A9 in osteosarcoma (OS) and its value as a diagnostic and therapeutic target in OS." (PMID 31055998, 2019). "On the other hand, downregulation of S100A9 inhibited cellular proliferation, migration, and tumor formation through inactivating MAPKs and nuclear factor-kappa B (NF-κB) signalings in human osteosarcoma cells." (PMID 32149126, 2020). "In this study, we investigated the expression of S100A9 protein in human osteosarcoma clinical samples and analyzed relevant clinicopathological characteristics." (PMID 27020242, 2016). "The expression of S100A9 was increased in human osteosarcoma issues and was positively correlated with clinical classification and survival rate." (PMID 27020242, 2016). "We aimed to understand the expression level, functions and mechanisms of S100A9 in human osteosarcoma for the first time." (PMID 27020242, 2016). "The expression of S100A9 protein was detected in 120 human osteosarcoma tissues and 40 normal human bone tissues using tissue microarrays analysis." (PMID 27020242, 2016). "Interestingly, we also observe an increase of S100A8 and S100A9 expression in the pre-metastatic lungs of osteosarcoma-bearing mice." (PMID 33233625, 2020). "S100A9 might be a significant role for predicting osteosarcoma prognosis and down-regulation of S100A9 could be used as a potential target for gene therapy." (PMID 27020242, 2016). "Nevertheless, little is known concerning the role of S100A9 in human osteosarcoma." (PMID 27020242, 2016). "Identified that S100A9 could be a biomarker for osteosarcoma by bioinformatics analysis; further research showed that this biomarker could also promote the proliferation and invasiveness of osteosarcoma cells." (PMID 37014329, 2023). "Therefore, we prone to put S100A9 as a significant parameter for predicting human osteosarcoma patients’ prognosis and S100A9 might be used as a potential target for cytokine therapy." (PMID 27020242, 2016). "The knockdown of S100A9 induced by RNA interference (RNAi) method in three osteosarcoma cell lines (U2OS, 143B, MG63) was applied to analyze the effects of S100A9 on cell proliferation, cell cycle distribution, migration, invasion and xenotransplanted tumors." (PMID 27020242, 2016).
Parkinson disease (8 papers, 2014 to 2025). A progressive degenerative disorder of the central nervous system characterized by loss of dopamine producing neurons in the substantia nigra and the presence of Lewy bodies in the substantia nigra and locus coeruleus. "S100A9 is a pro-inflammatory protein involved in neuroinflammation and central nervous system (CNS) neurodegenerative diseases, such as Alzheimer's and Parkinson's disease." (PMID 41080559, 2025). "S100A9 is intrinsically amyloidogenic and in vivo co-aggregates with amyloid-β peptide and α-synuclein in Alzheimer’s and Parkinson’s diseases, respectively." (PMID 37686007, 2023). "S100A9 can influence the aggregation kinetics and amyloid fibril structure of alpha-synuclein (α-syn), which is involved in Parkinson’s disease." (PMID 35743221, 2022). "Remarkably, S100A9 protofilaments and especially its annular species closely resemble similar amyloid structures of leading amyloid polypeptides such as Aβ and α-synuclein in AD and Parkinson’s disease, respectively and they are also cytotoxic towards SH-SY5Y neuroblastoma cells." (PMID 24240735, 2014). "Previously, in studies of ex vivo brain tissues in Alzheimer’s and Parkinson’s disease, mild cognitive impairment, and traumatic brain injury, we observed the extra and intracellular amyloid deposits of S100A9, but not S100A8." (PMID 34445262, 2021).
skin cancer (8 papers, 2014 to 2024). "S100A9 is a protein involved in the recruitment of immune cells and has been shown to be a molecule in the epidermal layer of the skin that controls skin tumor formation." (PMID 36338621, 2022). "Members of the larger S100 calcium-binding protein family, S100A8 and S100A9, regulate epithelial cell differentiation with increased expression of these proteins observed in inflammatory conditions and advanced stages of skin cancer." (PMID 28424693, 2017). "The up-regulation of S100A9 has been observed in colon, gastric, bladder, pancreatic, ovarian, breast thyroid, and skin cancers, while S100A9 is reduced in in esophageal squamous cell carcinoma." (PMID 27020242, 2016). "The rabbit skin tumours induced via blood infection displayed decreased expression of SLN, TAC1, MYH8, PGAM2, and APOBEC2 and increased expression of SDRC7, KRT16, S100A9, IL36G, and FABP9, as seen in tumours induced by local infections." (PMID 31340720, 2019). "Additionally, FABP5 plays a significant role in skin tumors; suppressing FABP5 or S100A9 expression impedes the proliferation and migration of cutaneous squamous cell carcinoma cells via the NF-κB pathway." (PMID 38596682, 2024).
steatosis (8 papers, 2015 to 2025). Increased lipid within the cytoplasm of cells. "However, biopsies from PNPLA3 variant carriers showed higher degree of steatosis (p = 0.022), DR (p = 0.044), IH (p = 0.027), and a higher number of αSMA+ portal/septal MFs (p = 0.040) and portal S100A9+ macrophages (p = 0.039) when compared with WT patients." (PMID 29150621, 2017). "Furthermore, we find that S100A9 is effective in predicting hepatic pathologic features, particularly steatosis and lobular inflammation." (PMID 25993652, 2015). "As regard histo-morphological parameters, the number of S100A9+ macrophages was directly correlated with NAS and DR extension and the number of CD206+ macrophages was inversely correlated with NAS, hepatocyte steatosis and lobular inflammation." (PMID 27310371, 2016). "In particular, the number of CD68+, S100A9+, and CD206+ macrophages was correlated with NAS score; moreover, the number of S100A9+ and CD206+ macrophages was correlated with steatosis and hepatocyte ballooning." (PMID 27310371, 2016). "Interestingly, in our study, liver expression of MDSC markers S100A8/S100A9/S100A12 was positively correlated with ATI, a measure of steatosis." (PMID 40257301, 2025).
Stroke (8 papers, 2015 to 2025). Sudden impairment of blood flow to a part of the brain due to occlusion or rupture of an artery to the brain. "Further studies are needed to elucidate whether S100A9 content or organization in stroke thrombi is associated with thrombus formation, resistance to revascularization therapies, and prognosis in stroke." (PMID 33402185, 2021). "Moreover, plasma calprotectin has been proposed as a diagnostic marker of AIS, and inhibition of S100A9 has been reported to suppress thrombus formation in experimental models of stroke." (PMID 33402185, 2021). "Since S100A8 and S100A9 also exhibit chemotactic properties by recruiting immune cells, it can be assumed that their increased expression 24 h after stroke in pigs also contributes to the development of the inflammatory response." (PMID 40332314, 2025). "Calcium-binding proteins—S100A8 and S100A9—were significantly elevated in the stroke-covered hemispheres." (PMID 40332314, 2025). "In our study, the enhanced expression of the S100A8 and S100A9 genes was already noticed in the ipsilateral hemisphere 24 h after stroke." (PMID 40332314, 2025). "In the post‐stroke follow‐up, we found that the ratio of S100A9+ cells in classical monocytes in the acute phase was positively correlated with the modified ranking scale score at 90 days after stroke onset." (PMID 39107960, 2024). "Nonetheless, another study demonstrated that thrombus formation was reduced in whole blood from S100A9 global knockout mice, thus reducing the incidence of thrombotic diseases, including MI and stroke." (PMID 39107960, 2024). "Because little was known about the composition of human stroke thrombi, we assessed for the first time the presence of S100A9 in thrombi retrieved from stroke patients." (PMID 33402185, 2021). "The presence of S100A9 in stroke thrombi suggests a possible inflammatory mechanism in clot formation, and further studies are needed to determine its influence in resistance to reperfusion." (PMID 33402185, 2021). "Notably, S100A9 was elevated in the ipsilateral hemisphere on day 7 post-stroke compared to 6 h, 24 h and 3 d (p < 0.05, p < 0.05 and p < 0.001, respectively)." (PMID 40332314, 2025). "S100A9 protein was present in all thrombi analyzed and quantification of thrombus constituents revealed that stroke thrombi contained on average 12.8% (IQR 1.34–28.89) red blood cells, 15.05% (4.84–26.65) platelets, 0.62% (0.35–1.17) leukocytes, and 3.52% (1.17–6.68) S100A9." (PMID 33402185, 2021). "Further, S100A9 was localized by immunostaining in stroke thrombi (n = 44)." (PMID 33402185, 2021). "Furthermore, S100A9 as part of calprotectin heterodimer was present in all thrombus obtained by mechanical thrombectomy in stroke patients and seems to be higher in thrombi from patients who died and in those of cardioembolic etiology." (PMID 33402185, 2021). "Therefore, investigating how S100A9 regulates the M/M phenotype in IS may provide a promising approach for stroke therapy." (PMID 39107960, 2024). "In the in vivo study, we generated the S100A9 conditional knockout (CKO) mice and compared the stroke outcomes with the control group." (PMID 39107960, 2024). "We further tested the S100A9‐specific inhibitor paqunimod (PQD), for its pharmaceutical effects on stroke outcomes." (PMID 39107960, 2024). "We identified Il-1β, Ccl2, Cybb, Wnt9b, as well as some pathway-specific genes such as S100a8 and S100a9 (IL-17 signaling) among the common pro-inflammatory and signaling molecules whose expression was affected by higher TMAO levels in post-stroke animals." (PMID 37175797, 2023). "In this study, the significant upregulation of S100a9 and Ttr in the CIR mouse brain indicated the successful induction of a stroke model and the reliability of the proteomics study." (PMID 26492191, 2015).
atopic dermatitis (7 papers, 2015 to 2025). "IL-6, S100A8, and S100A9 are three key regulators that display a positive biological relationship with atopic dermatitis and serve as major inflammatory markers under PM exposure." (PMID 35697899, 2022). "S100A8, S100A9, and S100A8/A9 are damage-associated molecular pattern molecules, which are highly elevated in patients suffering from atopic dermatitis and can be detected in some inflammatory reactions in activated keratinocytes." (PMID 28454097, 2017). "Increased expression of the homodimeric S100A8 (A8) and S100A9 (A9) alarmins and their Calprotectin (CP) antimicrobial hetero-complex has been reported in Inflammatory Skin Diseases (ISDs) such as Atopic Dermatitis (AD), but the functional consequences of this increase are not known." (PMID 40217087, 2025). "The reported list of inflammatory mediators found in atopic dermatitis includes S100A7, S100A8 S100A9, CCL2, CCL3, IL36A, IL36G, and IL36RN." (PMID 34925353, 2021).
cardiomyopathy (7 papers, 2014 to 2025). A disease of the heart muscle or myocardium proper. "Notably, S100A8 and S100A9 were found to have a unique specific expression pattern that was coincident with the DOX-induced cardiomyopathy in diabetic hearts." (PMID 27547188, 2016).